MIR4762 (microRNA 4762)
Synonyms: hsa-mir-4762
Gene: MicroRNA gene on chromosome 22 (45,760,524 to 45,760,598, forward strand). Ensembl gene ENSG00000264160.
Homologues: Orthologues: chimpanzee MIR4762 (100% identical).